BRCA1 (BRCA1 DNA repair associated)
Diseases named in the same sentence as BRCA1 in open-access papers (continued):
Sharing a sentence is not in itself a finding about the gene and the disease.
breast cancer (continued). "Only a relatively small proportion of breast cancers can be explained by the presence of high-penetrance genetic mutations, such as those in the BRCA1 and BRCA2 genes." (PMID 30781715, 2019). "One prospective cohort study evaluating over 9,000 mutation carriers, the majority from Europe, found the cumulative breast cancer risk to age 80 years was 72% for BRCA1 and 69% for BRCA2 carriers." (PMID 30915162, 2019). "In the present study on 27 families with male breast cancer, a BRCA1/2 mutation frequency of approximately 19% was observed, with BRCA2 mutations being about 4-times more common than BRCA1 mutations." (PMID 31528241, 2019). "The age at breast cancer onset was 40.3 years, 40.4 years, and 41.6 years in the BRCA1 L63X mutation-positive group, other BRCA1 mutation-positive group, and BRCA2 mutation-positive group, respectively." (PMID 31143373, 2019). "HR deficiency caused by hereditary and/or somatic mutations in BRCA1/2 or other DNA repair genes have been found not only in breast cancer but also in other types of cancer including ovarian or prostate cancer." (PMID 31549213, 2019). "In breast cancer patients, a more severe phenotype has been reported in individuals with double heterozygosity for disease-causing BRCA1 and BRCA2 mutations, two genes of the Fanconi anemia/Breast cancer pathway." (PMID 30305723, 2019). "As for breast cancers arising in BRCA1 mutation carriers, >80% belongs to the so-called “basal-like” subtype, accounting for the majority of triple negative breast cancers." (PMID 31225507, 2019). "In 2007, we reported that 2.5% of our incident breast cancer cases had one of the frequent Norwegian path_BRCA1 variants, while 23% of the incident ovarian cancers had one of these variants." (PMID 30678073, 2019). "TNBC is the most invasive and aggressive breast cancer that has a high mortality rate and disproportionately affects young AA women who have a much higher frequency of BRCA1 mutations." (PMID 33860286, 2019). "Genetic testing for the breast cancer susceptibility genes, BRCA1 (MIM# 113705) and BRCA2 (MIM# 600185), has become part of routine clinical care for patients with a personal or family history indicative of Hereditary Breast/Ovarian Cancer Syndrome (HBOC)." (PMID 30696104, 2019). "Germline BRCA1/BRCA2 pathogenic variants are an important factor in studying young women with breast cancer." (PMID 31491032, 2019). "In order to understand why BRCA1 mutation carriers have an increased risk of developing breast cancer, it is important to study the benign breast with all of its complexities in a physiological manner." (PMID 31771627, 2019). "Heritable mutations in BRCA1/2, especially BRCA1, increase the risk of developing ovarian and breast cancers; ~20% of HGSOCs are also mutated in the BRCA1/2 susceptibility genes due to a combination of germline and somatic mutations." (PMID 31197119, 2019). "T-distributed stochastic neighbour embedding (tSNE) analysis using the individual genes that constituted the T cell-inflamed signature score revealed two distinct clusters of BRCA1/2-deficient breast cancers." (PMID 31022191, 2019). "Our study demonstrated that the TAS in the saliva of breast cancer patients with the BRCA1 mutation was significantly higher compared to controls." (PMID 31597313, 2019). "In conclusion, BRRM was associated with lower overall and breast cancer-specific mortality rates than surveillance for BRCA1 mutation carriers." (PMID 31302855, 2019). "Despite intensified mechanisms of antioxidant defence (↑TAS, ↑Px), oxidative damage to salivary proteins (↑AGE) and lipids (↑MDA) is observed in patients with both breast cancer and the BRCA1 mutation." (PMID 31597313, 2019).
breast cancer (continued). "More importantly, the mostly recognized breast cancer susceptibility genes BRCA1 and BRCA2 participate in the process of HR." (PMID 31077156, 2019). "According to the estimates, about 10% of all ovarian cancer and 3%–5% of breast cancer cases are caused by mutations in the BRCA1 or BRCA2 genes." (PMID 31818005, 2019). "Literature revision supports that CTSO has been linked to BRCA1 by a mechanism that modulates BRCA1 expression in breast cancer." (PMID 31294536, 2019). "Breast cancers associated with BRCA1/2 mutations have a deficiency in homologous recombination repair, a mechanism of DNA double-strand breaks repair, the defect of which is synergistically lethal with the inhibition of single-strand DNA repair." (PMID 31336685, 2019). "Constitutional BRCA1 mutations are of high penetrance, occur in 10% of breast cancer patients and in 20% of young women with triple-negative breast cancers." (PMID 31413819, 2019). "The cumulative risk of breast cancer by age 80 years was estimated to 72% for BRCA1 carriers and 69% for BRCA2 carriers." (PMID 31060517, 2019). "Here, we report the prevalence of BRCA1/2 mutations in patients with high‐risk breast cancer from Inner Mongolia and Jilin, China, which was a part of a nationwide project on the detection of BRCA1/2 mutations in Chinese patients with hereditary breast cancer." (PMID 30968603, 2019). "Mutations in the BRCT domain of BRCA1 increase susceptibility to breast cancer by altering its molecular function through impaired protein interactions." (PMID 31240132, 2019). "To get a preliminary impression of this we examined a sample of breast tissue specimens from women with known mutations in the BRCA1 gene and another sample of basal-like breast cancers with the majority of the neoplastic cells being DP." (PMID 31619692, 2019). "Our findings support the notion that the presence of ovarian cancer in Pakistani breast cancer families increases the likelihood for the occurrence of BRCA1 mutation." (PMID 31528241, 2019). "Data from a previous Tunisian study showed that five out seven (71%) breast cancer patients with deleterious BRCA1 mutation exhibited triple negative tumors." (PMID 30975216, 2019). "Among studies published in Mexican population 53 pathogenic genomic variants of BRCA1/2 (24 in patients with early onset or a family history of breast cancer, 28 in unselected populations, and one in both unselected populations) have been reported." (PMID 31331294, 2019). "Differences in the patterns of CNAs were observed between PALB2-associated breast cancers and non-BRCA1/2/PALB2-associated breast cancers." (PMID 31428676, 2019). "As the lifetime risk of breast cancer is high, many women with PVs in BRCA1 or BRCA2 undergo risk-reducing mastectomy, which reduces the risk of breast cancer by 90–95%." (PMID 30832243, 2019). "These BRCA1 mutation carriers have significantly higher risk of developing breast cancer compared to the general population, with an estimated cumulative risk of 65% by the age of 70." (PMID 30995943, 2019). "Women who inherit a deleterious mutation in BRCA1 or BRCA2 are at increased risk of developing breast cancer." (PMID 31407530, 2019). "Through testing the entire sequences of BRCA1/2 genes with improved methodology and techniques, we estimate the combined prevalence of BRCA1/2 pathogenic variants among unselected breast cancer patients in Sweden to be closer to 2%." (PMID 30175445, 2019). "Nuclear‐enriched abundant transcript 1 is also a target of breast cancer susceptibility gene 1 (BRCA1), which is commonly mutated in hereditary cases of breast cancer." (PMID 30430751, 2019).
breast cancer (continued). "Numerous studies have revealed mutational signatures associated with breast cancer, namely signatures 1, 2, 3, 8, and 13, and also provide a mutational characterization of cancers with BRCA1 and BRCA2." (PMID 30934991, 2019). "In the Netherlands, all women diagnosed with breast cancer before the age of 40 are offered genetic testing for BRCA1, BRCA2 and CHEK2* 1100delC mutations." (PMID 30238178, 2019). "This is essential if a patient is considered to be at higher than average risk (i.e., having a strong family history of breast cancer or personal history of breast cancer, benign breast disease, or inherited BRCA1 and/or BRCA2 mutations)." (PMID 31354818, 2019). "The most cited biomarker is BRCA1 mutation as a predisposing marker in breast cancer with 682 different papers discussing this." (PMID 31796060, 2019). "The enhanced risk and high penetrance of breast cancer due to a BRCA1 germline mutation are attributable to the tumor-suppressor role of the BRCA1 protein, which modulates homologous recombination (HR)-dependent DNA repair." (PMID 30683142, 2019). "A 42-year-old woman with a BRCA1 mutation developed DCIS as a primary breast cancer during surveillance only 4 months after genetic testing." (PMID 30980249, 2019). "To address this issue, we aimed to investigate the differences in AAO of breast cancer among BRCA1 mutation carriers by studying 311 DNA-repair genes which are contributing to genome stability along with BRCA1 and BRCA2." (PMID 31395037, 2019). "Women with BRCA1 or BRCA2 mutations strongly expressed preferences for breast cancer risk reduction and preservation of fertility." (PMID 30980249, 2019). "In breast cancer, germ line mutations in BRCA1 and BRCA2 are examples of genomic instability that increases tumor susceptibility." (PMID 29478325, 2019). "Deficiencies in HR have been detected both in BRCA1/2 germline mutation–associated and remarkable fraction BRCA1/2 wild-type breast cancer patients." (PMID 31077156, 2019). "Of this, the prevalence of BRCA1 mutation alone among breast cancer patients was 11% (95% CI: 4–21%)." (PMID 30898109, 2019). "This final predictor, termed HRDetect, was applied to a cohort of 560 cases of breast cancer and showed a 98.7% of detecting BRCA1/2-deficient tumors." (PMID 30934991, 2019). "More specifically, previous studies demonstrated that RANKL mediates progesterone-driven mammary carcinogenesis and RANK/RANKL signalling controlled BRCA1 mutation-driven mammary tumours." (PMID 31181781, 2019). "Family history of breast cancer, especially having inherited germline BRCA1/2 mutation, greatly increases lifetime breast cancer risk." (PMID 31889127, 2019). "Research using BRCA1 gene mutation in breast cancer would help us in making assumptions on how this disease is transmitted from generation to generation." (PMID 31759379, 2019). "Approximately 5–10% of breast cancers are hereditary and the vast majority of them are due to germline mutations in BRCA1 and BRCA2 tumor suppressor genes." (PMID 30621730, 2019). "Persons carrying mutations in the BRCA1/2 gene are more likely to develop breast cancer (men and women), ovarian cancer in women and prostate cancer in men." (PMID 30693378, 2019).
breast cancer (continued). "Previous studies have suggested that the prevalence of BRCA1 and 2 mutations in the Lebanese population is low despite the observation that the median age of breast cancer diagnosis is significantly lower than European and North American populations." (PMID 30675319, 2019). "To refine the spectrum of BRCA1/2 mutations and to accurately estimate the prevalence of mutation in the Pakistani population, we studied 539 breast cancer patients selected for family history and age of diagnosis." (PMID 31528241, 2019). "BRCA1 mutation carriers face extremely high lifetime risks of breast cancer estimated to be 60% by age 70, although penetrance estimates up to 85% have been reported." (PMID 31069010, 2019). "More than 75% of BRCA1-mutated breast cancers have a triple-negative phenotype and are classified as basal-like." (PMID 31413819, 2019). "One clear example of its role in tumorigenesis is the fact that PP1 interacts with the breast cancer susceptibility gene BRCA1." (PMID 31225502, 2019). "It therefore seems unlikely that the presence of BRCA1/BRCA2 mutations is the reason for the raised breast cancer risks observed in this cohort." (PMID 30496607, 2019). "In summary, we detected 17 BRCA1/2 mutations in 18 of 216 (8.3%) index patients with high‐risk breast cancer." (PMID 30968603, 2019). "Individuals with BRCA1 mutations are predominantly predisposed to estrogen receptor (ER)-negative breast cancer, whereas other known susceptibility loci for breast cancer are stronger associated with ER-positive tumors." (PMID 30956778, 2019). "The 24 PALB2-associated breast cancers harbored gains of 16p and losses of 13p and 16q less frequently than the 683 ER−/HER2− and ER+ non-BRCA1/2/PALB2-associated breast cancers (P < 0.05, Fisher’s exact test and bootstrapping-corrected)." (PMID 31428676, 2019). "Both tubes and ovaries were removed in patients with a strong family history of ovarian and/or breast cancer and those positive for BRCA1/2 genetic mutation." (PMID 31915530, 2019). "We report biallelic BRCA1 mutations c.181T > G (p.Cys61Gly) and c.5096G > A (p.Arg1699Gln) in a woman with breast cancer diagnosed at the age of 30 years." (PMID 31347298, 2019). "HR defects occur in between 25 and 40% of breast cancers, from both germline and somatic mutations of key components of the HR pathway such as BRCA1/BRCA2." (PMID 31320901, 2019). "The third pathogenic variant found in our cohort, BRCA1 c.5431C > T has been documented in 3 unrelated patients with breast cancer of Greek origin." (PMID 31488070, 2019). "Women mentioned the hereditary predisposing factor (e.g., “I am BRCA1 and understand that getting breast cancer again is a great possibility.”)." (PMID 31186965, 2019). "The main risk factor for familial breast cancer is the presence of mutations in BRCA1 and BRCA2 genes." (PMID 31341521, 2019). "We demonstrated that saliva from breast cancer patients with the BRCA1 mutation is characterized by enhanced antioxidant capacity and a higher degree of oxidative damage to proteins and lipids." (PMID 31597313, 2019). "This triple-negative phenotype of breast cancer, common among African American women, is strongly associated with BRCA1 mutations and is more likely to resist hormone therapy with an aggressive behavior." (PMID 30806064, 2019). "Compared to the general population, the risk of breast cancer in BRCA1 and BRCA2 mutation carriers increases by 10‐ to 20‐fold (Ludwig, Neuner, Butler, Geurts, & Kong, 2016; Nelson, Huffman, Fu, Harris, & U.S. Preventive Services Task Force, 2005)." (PMID 30968603, 2019).
breast cancer (continued). "Patients with breast cancer who have a germline BRCA1/BRCA2 mutation are at increased risk of ipsilateral and contralateral tumours compared with those presenting with sporadic disease." (PMID 30689103, 2019). "We have found that SAHA, an FDA-approved HDAC inhibitor, decreases the CSC-like population in both BRCA1-deficient and -competent breast cancer cells." (PMID 31273285, 2019). "Women who are germline BRCA1 mutation carriers have a 15% increased risk of developing breast cancer and, if diagnosed, a 40–60% risk of a TNBC diagnosis." (PMID 33860286, 2019). "By using trial registration data from the Japanese hereditary breast and ovarian cancer syndrome (HBOC) consortium, we aimed to explore the clinicopathological characteristics of breast cancer patients with the Japanese founder mutation BRCA1 L63X." (PMID 31143373, 2019). "Another example is testing for BRCA1/2 genes, which constitute well-established pharmacogenomic biomarkers for breast cancer, as specific mutations in these genes have been associated with a greatly increased risk of developing breast cancer." (PMID 31427963, 2019). "Recently, a PARP (poly-ADP-polymerase) inhibitor—through the underlying mechanism of inhibiting DNA repair, has demonstrated good efficacy against BRCA1-associated breast cancer, which usually refers to TNBCs." (PMID 31555586, 2019). "Overall, as previous studies showed 3%–28% of familial breast cancer cases are linked to variants in BRCA1 and BRCA2 genes." (PMID 31131559, 2019). "The only effective risk-reducing options for women with BRCA1 mutations are prophylactic mastectomy and oophorectomy, which can achieve 90% and 50% reduction in breast cancer risk, respectively." (PMID 30995943, 2019). "Impaired expression of BRCA1 can also occur through epigenetic silencing, leading to an increased risk of breast cancer." (PMID 31771139, 2019). "The BRCA1/2 mutation positivity prevalence was also 19% in the patients with breast carcinoma histories in their first-degree relatives." (PMID 30713775, 2019). "In the USA, in those with breast carcinoma histories in their families, the BRCA1/2 mutation prevalence was 12%." (PMID 30713775, 2019). "In our study, we found a BRCA1/2 mutation prevalence of 24.2% in the patients with breast carcinomas showing triple-negative features." (PMID 30713775, 2019). "Breast cancer (BC) prognosis in BRCA1 and BRCA2 mutation carriers has been reported contradictorily, and the significance of variables influencing prognosis in sporadic BC is not established in BC patients with hereditary BRCA1/BRCA2 mutations." (PMID 31141992, 2019). "Overall, BRCA1/2 mutations are frequently seen in young women and women with breast carcinomas showing triple-negative features." (PMID 30713775, 2019). "This shows that, as in other Turkish populations, the BRCA1/2 mutation frequency in women with high-risk breast carcinomas increases from 19% to 37%." (PMID 30713775, 2019). "It is recommended to check for BRCA1/2 mutations in all high-risk breast carcinoma patients in the Turkish population." (PMID 30713775, 2019). "In the women with breast carcinomas showing triple-negative features under the age of 40 years old, the BRCA1/2 mutation prevalence was 37.5%." (PMID 30713775, 2019). "The breast cancer 1 gene (BRCA1) and the breast cancer 2 gene (BRCA2) are the two most-studied BC susceptibility genes." (PMID 30940775, 2019). "In this retrospective study, the BRCA1/2 mutation prevalence in high-risk breast carcinoma patients in a Turkish population was investigated." (PMID 30713775, 2019).